CRP (C-reactive protein)
Diseases named in the same sentence as CRP in open-access papers (continued):
Sharing a sentence is not in itself a finding about the gene and the disease.
leukocytosis (continued). "Clinically relevant cut-offs for leukocytosis(>10.0 x109/L), lymphopenia(< 1.1 x109/L), elevated C-reactive protein(>100mg/L), LDH(>250U/L) and D-dimer(>1mg/L) had higher odds of severe disease and greater risk of mortality." (PMID 33206661, 2020). "Initial bloods revealed leukocytosis with left shift and mildly elevated C-reactive protein (CRP), ALP and GGT, but normal electrolytes and renal function." (PMID 32460761, 2020). "In our study, patients who had NOSE did not experience significant postoperative morbidity or laboratory data changes, such as leukocytosis, or CRP level elevation, than the conventional group." (PMID 32632708, 2020). "His physical examination was remarkable, his abdomen was diffusely tender and his lab tests reveal an increasing in inflammatory markers: C-reactive protein (CRP) 256 mg/l, leukocytosis 14(× 10 /ul),with left shift 92% neutrophils." (PMID 32375832, 2020). "The most common laboratory abnormalities seen in pregnant women infected with SARS-CoV-2 were elevated C-reactive protein (CRP), neutrophilia, and leukocytosis." (PMID 33062333, 2020). "Disease activity in Schnitzler syndrome is routinely assessed by clinical evaluation (rash, fever, pain), leukocytosis and CRP level." (PMID 33324407, 2020). "Systemic inflammation is revealed by elevated levels of C-reactive protein, together with leukocytosis, neutrophilia and/or monocytosis." (PMID 33324407, 2020). "In terms of laboratory findings, approximately 48%, 43% and 36% of infected pregnant women had elevated CRP, lymphopenia, and leukocytosis, respectively." (PMID 33093582, 2020). "The bronchial lavage cultures showed B. trematum susceptible, according to EUCAST version 7.0; PK/PD (Non-species related) breakpoints, to the currently administered piperacillin/tazobactam, while the CRP and leukocytosis had mildly decreased." (PMID 32189223, 2020). "Blood tests revealed leukocytosis (10,000 /μL) and an elevated C-reactive protein (CRP) level (5.0 mg/dL)." (PMID 31931763, 2020). "Both are characterized by fever, abdominal/chest pain, elevation of C-reactive protein, and leukocytosis." (PMID 33072117, 2020). "Overall, 14 patients (64%) exhibited intermittently elevated levels of acute phase reactants including SAA (n = 14; 64%), CRP (n = 8; 36%) and leukocytosis (n = 10; 46%)." (PMID 33334368, 2020). "In the studies that reported laboratory findings, 147 pregnant women were included, and among them, 49% had elevated CRP, 31.3% had lymphopenia, 28.6% had neutrophilia, and 12.2% had leukocytosis." (PMID 33062333, 2020). "Laboratory testing revealed leukocytosis of 13,000 cells/mm3 and elevated C-reactive protein of 44.3 mg/L." (PMID 32891177, 2020). "Leukocytosis was noted in 52 (28.1%) children and a serum CRP level of > 40 mg/L (normal, < 5 mg/L) was found in 55 (29%) children." (PMID 33081701, 2020). "Laboratory tests disclosed leukocytosis with neutrophilia, anemia, thrombocytosis, and increased erythrocyte sedimentation rate, C-reactive protein (CRP), aspartate aminotransferase (AST), lactate dehydrogenase and ferritin (T0)." (PMID 32653009, 2020). "For our patients, laboratory tests supporting KD diagnosis included changes of markers at acute phase such as leukocytosis, elevated CRP, hypoalbuminemia, mild elevations of ALT, and mild elevations of CK-MB and thrombocytosis on day 12 of illness." (PMID 31987031, 2020). "In the current study, along with leukocytosis, a higher serum CRP level > 40 mg/L (normal, < 5 mg/L) was found in around 30% of the cases." (PMID 33081701, 2020). "Extended laboratory tests 2 weeks later showed anemia (hemoglobin 11.3 g/dl), increased lactate dehydrogenase (278 U/l, normal ≤ 250), progredient CRP (18.27 mg/dl), and progressive leukocytosis (56.090/μl)." (PMID 32072333, 2020). "All but two patients had clinical signs of pneumonia (elevated C-reactive protein, leukocytosis, purulent tracheal secretions, pulmonary infiltrates, or typical signs in bronchoscopy)." (PMID 31924246, 2020).
leukocytosis (continued). "Four neonates with EONS showed metabolic acidosis (57.14%), five had elevated CRP levels (71.42%), three had leukocytosis/leucopenia (42.85%), and one had positive findings of pneumonia on chest x-ray (14.28%)." (PMID 32190434, 2020). "Abnormal laboratory parameters involved in cases of liver abscess discussed in the literature include leukocytosis, anemia, and elevated acute phase reactants (erythrocyte sedimentation rate, CRP, and altered liver enzyme levels)." (PMID 32266189, 2020). "An increased concentration of platelets in the blood of RA patients was directly related to the signs of inflammation, such as elevated ESR, C-reactive protein and other acute-phase proteins, the appearance of rheumatoid factor, leukocytosis, etc.." (PMID 33322373, 2020). "Serum markers of systemic inflammation (i.e., leukocytosis, lymphopenia, C-reactive protein [CRP] elevation, and inflammatory cytokines) are well-known indices of poor survival." (PMID 32611346, 2020). "Inflammatory markers (e.g., acute phase proteins and especially C-reactive protein (CRP), leukocytosis, thrombocytosis) are associated with prognosis in several malignancies, including head and neck cancer/squamous cell carcinoma (HNSCC)." (PMID 33066437, 2020). "The main laboratory findings included leukocytosis, lymphopenia, thrombocytopenia, and elevated C-reactive protein." (PMID 32685412, 2020). "We looked into the impact of CRP/PNI on overall survival (OS) in laryngeal cancer and contrasted the predictive value of platelet count, CRP, PNI, leukocytosis, lymphocyte counts, anemia, and CRP/PNI." (PMID 31312573, 2019). "Laboratory findings reveal high leukocytosis, elevated C-reactive protein, and in the most severe cases hypoalbuminemia as well as acute kidney injury." (PMID 30945014, 2019). "Severe leukocytosis and higher CRP, as well as lower albumin levels, were common in AKI patients compared with non-AKI patients." (PMID 30942133, 2019). "Laboratory exams revealed anemia, leukocytosis and increased erythrocyte sedimentation rate, as well as C-reactive protein rate and serum biomarkers indicative of myocardial injury." (PMID 30810692, 2019). "The laboratory tests showed mild leukocytosis (12,330/μL) with neutrophilia (9680/μL), and increased inflammatory biomarkers (CRP 52.46 mg/L, ESR 29 mm/h)." (PMID 31626134, 2019). "Laboratory tests revealed leukocytosis (15.,800 white blood cells/mm3 with 50.3% neutrophils), a slight increase in serum C-reactive protein (11.9 mg/L) and normal procalcitonin values (< 0.12 ng/mL)." (PMID 31060497, 2019). "Upon admission, blood test results performed on 20 January 2018 revealed signs of an infection characterized by leukocytosis (18,800/mcl) with 81% neutrophils and high C-reactive protein levels (CRP = 427.5 mg/L)." (PMID 30781742, 2019). "When a patient presents with long-term fever, high C-reactive protein level, leukopenia/leukocytosis, and multiple or single pulmonary nodules with a “halo sign” and air bronchogram on computed tomography, a possibility of PPL should be considered." (PMID 30736822, 2019). "There were 26 adverse events reported, including pain (eight patients), leukocytosis (eight patients), increased C-reactive protein level (eight patients), swelling (one patient), and fever (one patient)." (PMID 30820353, 2019). "Laboratory investigation revealed leukocytosis (white blood cell count: 12,100 cells/μl) and elevated C-reactive protein (CRP) level (serum CRP: 164 mg/dl)." (PMID 31500608, 2019). "In a retrospective review of 33 patients with mycotic aneurysm who underwent surgery, preoperatively, signs of infection (elevated CRP and leukocytosis) were found in 79% and fever was found in only 46%." (PMID 31467741, 2019). "Laboratory findings that are useful in CD are hypoalbuminemia, elevation of the erythrocyte sedimentation rate and C-reactive protein, anemia, or leukocytosis." (PMID 30846003, 2019).
leukocytosis (continued). "In the univariate analysis, PNI (p<0.001), CRP (p=0.04), lymphocyte counts (p<0.001), leukocytosis (p=0.015), hypoalbuminemia (p=0.037), and CRP/PNI (p=0.010) were found to have a significant impact on OS." (PMID 31312573, 2019). "When a patient presents with long-term fever, high C-reactive protein concentrations, leukopenia/leukocytosis, and multiple or single pulmonary nodules with a “halo sign” and air bronchogram on CT scan, a possibility of PPL should be considered." (PMID 30736822, 2019). "Laboratory values, including leukocytosis, elevated polymorphonuclear neutrophils (PMNs) and elevated C-reactive protein (CRP) used in the evaluation of potential appendicitis are all nonspecific markers of inflammation." (PMID 33178945, 2019). "LPS-induced rats showed significant leukocytosis, and elevated serum levels of CRP, TNF-α, IL-1β, IL-6, IL-8, MCP-1, malondialdehyde (MDA) and 8-hydroxy-2′-deoxyguanosine (8-OHdG), accompanied with diminished antioxidants." (PMID 30858869, 2019). "During hospitalization, the patient had a fever and leukocytosis, and was diagnosed with bronchopneumonia, treated with vancomycin and tazobactam with a reduction in C-reactive protein and leukocytosis." (PMID 31691760, 2019). "Chronic dialysis patients with anal abscess often develop leukocytosis, anemia, elevated C-reactive protein and hypoalbuminemia." (PMID 30916172, 2019). "The CRP/PNI ratio should be assessed together with leukocytosis in laryngeal cancer patients in further studies." (PMID 31312573, 2019). "We report the case of a 53-year-old female patient with a pheochromocytoma that presented with fever and weight loss of 5% in one month along with normocytic anemia, thrombocytosis, leukocytosis, and elevated C-reactive protein." (PMID 31019814, 2019). "PID is often diagnosed clinically on the basis of fever, dull aching pelvic pain and cervical tenderness, vaginal mucopurulent discharge, leukocytosis and elevated C-reactive protein (CRP) levels." (PMID 31858287, 2019). "This was consistent with a previous study, which showed that leukocytosis was seen in one-fourth of the patients and a moderately elevated CRP > 40 mg/L was seen in nearly two-thirds of the patients." (PMID 31370781, 2019). "Laboratory examinations revealed moderate leukocytosis (16.93 × 109/L, normal range 3.5–9.5 × 109/L), increased neutrophils (14.3 × 109/L, normal range 1.8–6.3 × 109/L), and elevated C-reactive protein (30.77 mg/L, normal range 0–10 mg/L)." (PMID 31703558, 2019). "A recent study indicated that leukocytosis, together with CRP, is a good predictor of a positive CT, particularly in patients with right iliac fossa pain." (PMID 30658580, 2019). "Haematological abnormalities indicative of inflammation were also observed as whole blood analysis demonstrated predominant leukocytosis and elevated C-reactive protein levels." (PMID 31088357, 2019). "Biochemical analysis showed leukocytosis, anemia, increased C-reactive protein, prolonged prothrombin time, pancytopenia, hyponatremia." (PMID 30733936, 2019). "Our analysis also revealed presence of biochemical & haematological evidence of inflammation in the form of elevated C-reactive protein and leukocytosis in a majority of our study populace." (PMID 31088357, 2019). "A meta-analysis has nonetheless shown that the combination of a CRP threshold of > 50 and elevated leukocytosis (> 15 G/L) had a high PPV for differentiating between emergency abdominal pathologies, requiring CT, and those which are not emergencies." (PMID 30658580, 2019). "Blood investigations showed leukocytosis at 12.0 × 109/L, C-reactive protein (CRP) at 34 mg/l, and serum sodium and potassium levels were within normal limits." (PMID 31126322, 2019). "Leukocytosis, increased neutrophil rate, increased C-reactive protein (CRP), increased bilirubin, procalcitonin and IL-6 are helpful in diagnosis." (PMID 31938617, 2019).
leukocytosis (continued). "At 1 month of age, an elevation in C-reactive protein (CRP) up to 3 mg/dL and leukocytosis (white blood cell [WBC] count of 35,400/mm3) were observed." (PMID 29506479, 2018). "In both cases, no adverse immune reaction towards the xenogenic cells with respect to leukocytosis or C-reactive protein levels was reported." (PMID 30149650, 2018). "The patient was placed on complete bowel rest with serial abdominal examinations to rule out progression to overt appendicitis, given the location of the pain in the context of leukocytosis with elevated CRP." (PMID 30186884, 2018). "The laboratory tests, on the day of admission, revealed leukocytosis with neutrophilia, anemia, thrombocytosis, hypernatremia, hypoalbuminemia, elevated C-reactive protein (CRP), and erythrocyte sedimentation rate (ESR)." (PMID 30101141, 2018). "Initial laboratory findings revealed mild leukocytosis (10.7 × 109/L), elevated neutrophil granulocytes (89% of the leukocytes) and elevated C reactive protein (CRP) (373.2 mg/L)." (PMID 29995757, 2018). "Laboratory study revealed that the majority (89.4%) of patients had elevated CRP while leukocytosis, thrombocytosis, and anemia occurred in less than 50% of cases." (PMID 29686701, 2018). "Some changes in laboratory test results were also found, suggesting the inflammatory process with elevated ESR, increased CRP, leukocytosis, and elevated neutrophil ratio, which was similar to the findings of a previous study." (PMID 30410939, 2018). "Commonly, the symptoms (foul smelling lochia, abdominal pain, and fever) started 3–10 days after vaginal delivery, and leukocytosis and a raised CRP value were present." (PMID 29973773, 2018). "Her blood results showed elevated C-reactive protein (CRP, upon admission 256.7 mg/L; reference < 7.5 mg/L) and leukocytosis (leukocytes upon admission 21.5 10^9/L, reference 3.5–10.0 10^9/l) with slight monocytosis present in the leukogram." (PMID 29347961, 2018). "Laboratory findings included leukocytosis with peripheral blood eosinophilia and elevated erythrocyte sedimentation rate, C-reactive protein, and serum creatinine." (PMID 30761231, 2018). "Laboratory studies revealed mild leukocytosis, increased levels of serum lipase, amylase, and C-reactive protein (CRP)." (PMID 30071846, 2018). "Laboratory findings included leukocytosis and discretelyincreased C-reactive protein, as well as aspartate aminotransferase (AST) and alanineaminotransferase (ALT) at the upper limits of normality." (PMID 30369664, 2018). "Meanwhile, laboratory studies revealed the presence of leukocytosis [26,780 white blood cells (WBCs)/μL] with 1 mg/L C-reactive protein (CRP)." (PMID 30501615, 2018). "At least one biological criterion was mentioned in 64% of trials and mandatory in 6%: mostly leukocytosis or C-reactive protein." (PMID 30509278, 2018). "Other factors demonstrated to have prognostic importance in our cohort were age, admission from ED or ICU, functional dependency, malnutrition, cancer, reduced GFR, hypoalbuminemia, leukocytosis, and elevated C-reactive protein." (PMID 29381733, 2018). "Initial laboratory testing revealed leukocytosis, anemia, elevated C-reactive protein (CRP), hypoalbuminemia; and normal AST/ALT and BUN/creatinine." (PMID 30068330, 2018). "Additional laboratory tests showed increases in leukocytosis,C-reactive protein, AST, ALT, and total bilirubin." (PMID 30369664, 2018). "For example, some authors defined PIS with regards to fever and leukocytosis, while others consider fever and elevated CRP." (PMID 29650053, 2018). "Clinically, omental infarction often presents similarly to acute appendicitis with right lower quadrant (RLQ) tenderness, leukocytosis, elevated C-reactive protein (CRP), and anorexia." (PMID 30186884, 2018). "Building a ROC curve to determine an optimal cut-off in a diagnostic test for lung inflammation seems less relevant as common markers as C-reactive protein, sedimentation rate and leukocytosis are robust biomarkers." (PMID 30176828, 2018).
leukocytosis (continued). "Blood examination showed leukocytosis (white blood cell: 15,980/μL with neutrophil predominance) and C reactive protein 5.59 mg/L, with normal renal and liver function." (PMID 29390583, 2017). "Blood examination showed leukocytosis with neutrophil predominance and C reactive protein elevation." (PMID 29390583, 2017). "Symptoms of anastomotic leakage include abdominal pain, peritoneal irritation, backache, lumbago, and continuous remittent fever over 38 °C, accompanied by leukocytosis and an elevated C-reactive protein level." (PMID 28693546, 2017). "An increase of inflammation biological parameters is frequent such as leukocytosis with predominance of neutrophils, and increased C-reactive protein (CRP)." (PMID 28451043, 2017). "The peak of inflammatory markers such as CRP, procalcitonin, leukocytosis is slower than the clinical symptoms." (PMID 28729928, 2017). "With regard to systemic manifestations, leukocytosis and elevation of C-reactive protein were common in the current study (68.7% and 81.9% respectively), indicating an infected or inflamed state." (PMID 28972988, 2017). "In advanced cancer patients, a variety of biological factors such as leukocytosis, lymphocytopenia, and C-reactive protein have been identified as having a definite correlation with prognosis." (PMID 28124528, 2017). "Leukocytosis and elevated levels of CRP and aspartate aminotransferase were noted in most of the patients." (PMID 28149700, 2017). "Patients with pancolitis had more pronounced anemia, leukocytosis and higher CRP and sedimentation than distal colitis." (PMID 29232715, 2017). "Baseline blood tests showed leukocytosis (10.4 × 109/L [7.8–12.7]) and elevated CRP (23.3 mg/L [10.5–55.7])." (PMID 28683717, 2017). "Some studies have reported that physical exercise can promote an immediate inflammatory response marked by leukocytosis, increased production of reactive oxygen species, and increased C-reactive protein levels." (PMID 28793058, 2017). "Neutrophilic leukocytosis was evident in the majority of patients (22 of 24—91.6%) while inflammation indicators (CRP) were increased in 23 patients (95.8%)." (PMID 28740847, 2017). "Leukocytosis with neutrophilia, thrombocytosis, elevated liver enzymes and C-reactive protein (CRP), and hyperferritinemia are present in AOSD, although these results are non-specific." (PMID 28436448, 2017). "Laboratory tests showed a leukocytosis of 16,510/μl, and elevated levels for the C-reactive protein (CRP, 17.5 mg/dl) and creatine-kinase (CK, 669 U/l)." (PMID 28807000, 2017). "One of these patients showed microbiological testing results indicating infection with methicillin-resistant Staphylococcus aureus (MRSA) and methicillin-resistant S. epidermidis (MRSE) with leukocytosis and elevated CRP levels." (PMID 27535061, 2017). "Biochemical analyses showed marked leukocytosis with neutrophilia (20,000/mm3, neutrophils 90%), elevated CRP (150 mg/L, normal values <6), and troponin T (78 ng/L, normal values <38)." (PMID 28232838, 2017). "Despite the difference in age in comparison with our patient, we conclude that a very elevated CRP, leukocytosis, and fever can also occur in PA." (PMID 28588003, 2017). "Inflammatory markers including leukocytosis, erythrocyte sedimentation rate, and C-reactive protein were higher in patients with CPA." (PMID 28006828, 2016). "The laboratory findings in the study were leukocytosis (66%), thrombocytosis (73%), sterile pyuria (24.5%), high levels of CRP (92.1%), and high levels of ESR (94.9%)." (PMID 27757208, 2016). "Leukocytosis (>10,000 WBCs/μL), positive CRP (>0.3 mg/dL) and hyponatremia (<135 mEq/L) were noted in 42 % (5/12), 75 % (9/12) and 44 % (4/9) of the patients, respectively." (PMID 27836006, 2016).